MGMT (O-6-methylguanine-DNA methyltransferase)
Diseases named in the same sentence as MGMT in open-access papers (continued):
Sharing a sentence is not in itself a finding about the gene and the disease.
glioblastoma (continued). "Moreover, several studies have demonstrated that epigenetic silencing of MGMT is a relevant prognostic factor in patients with glioblastoma, anaplastic glioma and low grade glioma." (PMID 21269507, 2011). "Epigenetic silencing of MGMT by promoter methylation has been detected in 36% of primary glioblastomas, 75% of secondary glioblastomas, and 40% of pediatric cases and confers a better prognosis for both adult and pediatric patients who receive temozolomide treatment." (PMID 20652056, 2010). "Breakout box 1: MGMT hypermethylation as a predictive marker in glioblastomas." (PMID 19333441, 2009). "None of these substances, except TMZ, could improve the prognosis of glioblastoma in a first-line setting, and the improvement is largely limited to patients with a methylated MGMT promoter." (PMID 19725960, 2009). "Special emphasis will be put on the introduction of those molecular biomarkers that have been established in glioma diagnostics, namely MGMT promoter hypermethylation in glioblastomas and deletion of chromosome arms 1p and 19q in patients with oligodendroglial tumors." (PMID 19333441, 2009). "We then investigated MGMT promoter methylation by pyrosequencing in five glioblastomas with frozen tissue and seven cases each with frozen tissue, intraoperative smears and FFPE samples meeting the selection criteria of >70% neoplastic component and <50% necrosis." (PMID 19536096, 2009). "Similarly, glioblastomas show heterogeneous patterns of MGMT protein expression often with regions within the same tumour displaying widely different staining patterns." (PMID 19536096, 2009). "In fact, first steps have been undertaken in supplementing classical histopathological diagnosis by the use of molecular tests, such as MGMT promoter hypermethylation in glioblastomas or detection of losses of chromosome arms 1p and 19q in oligodendroglial tumors." (PMID 19333441, 2009). "Methylation of the O6-methylguanine-DNA methyltransferase (MGMT) promoter is an important prognostic marker in glioblastoma (GBM); however, its implementation in clinical practice remains understudied." (PMID 39907975, 2025). "Leveraging the high sensitivity of 18F-DOPA PET imaging for glioblastoma, the selected radiomics features, especially TBRmax, from pre-RT images can effectively stratify the patient cohort with un-methylated MGMT and wild-type IDH1, identifying the patients who may benefit most from DERT." (PMID 40881875, 2025). "Analyzing epimutations affecting the key regulatory area of the MGMT promoter, the hazard ratio (HR) was 1.07 (95% CI 0.79–1.45) and 0.80 (0.59–1.08) for right- and left-sided colon cancer, respectively, 1.13 (0.78–1.64) for glioblastoma, and 1.11 (0.83–1.48) for diffuse large B-cell lymphomas." (PMID 39980037, 2025). "Similarly, glioblastoma MGMT prediction studies exemplify how imaging–omics models could be used in practice to reduce invasive biopsies." (PMID 41301005, 2025). "Similarly, in glioblastoma procedures, adjuvant temozolomide usage is guided by MGMT methylation." (PMID 41311621, 2025). "Furthermore, several studies did not include biomolecular markers of glioblastoma, such as MGMT methylation and IDH mutation status, with their proportional hazards models, thus limiting the applicability of their results." (PMID 40612291, 2025). "Notably, these nanoparticles conferred superior cytotoxicity in TMZ-resistant glioblastoma T98G cells, attributed to the amplification of intracellular reactive oxygen species (ROS) and DNA damage, along with MGMT (O-6-methylguanine-DNA methyltransferase) expression suppression." (PMID 40429865, 2025). "In this study, we aimed to develop a novel predictive model to estimate individual survival for patients diagnosed with glioblastoma (GBM), focusing on key variables such as O6-Methylguanine-DNA Methyltransferase (MGMT) methylation status, age, and sex." (PMID 39992425, 2025).
glioblastoma (continued). "Additionally, methylguanine-DNA methyltransferase (MGMT) methylation might influence the incidence of PsP in glioblastomas." (PMID 39134744, 2025). "The mutation status of the 21 patients with glioblastoma was as follows: all 21 had isocitrate dehydrogenase (IDH)-wildtype; 11 had a telomerase reverse transcriptase (TERT) promoter C228T mutation, and 10 had an O6-methylguanine-DNA methyltransferase (MGMT) methylation." (PMID 40866807, 2025). "Moreover, the presence of MGMT promoter methylation in 30% to 50% of IDH wild-type glioblastomas might be indicative of a somewhat improved prognosis and a beneficial reaction to alkylating chemotherapy agents, such as Temozolomide (TMZ)." (PMID 39248068, 2025). "However, MGMT promoter methylation has been reported to be less frequent compared to glioblastoma." (PMID 40244270, 2025). "Overall survival in months in glioblastoma (GBM) subgroup between O6-methylguanine-DNA methyltransferase (MGMT) status and between larger/lower than median region of interest (ROI) volume in all ROIs segmented through deep learning methods." (PMID 41476598, 2025). "Progression free survival in months in glioblastoma (GBM) subgroup between O6-methylguanine-DNA methyltransferase (MGMT) status and between larger/lower than median region of interest (ROI) volume in all ROIs segmented through deep learning methods." (PMID 41476598, 2025). "Multiple studies have indicated alterations in MGMT methylation or activity in patients with glioblastoma (GBM) following chemotherapy, and the expression of MGMT in some recurrent cases differed from that in the original tumor." (PMID 38255825, 2024). "Moreover, MGMT promoter hypermethylation may increase sensitivity to alkylating agents like Dacarbazine and Temozolomide, as observed in patients with glioblastoma, advanced melanoma, and neuroendocrine tumors." (PMID 39594133, 2024). "Accurate and non-invasive estimation of MGMT promoter methylation status in glioblastoma (GBM) patients is of paramount clinical importance, as it is a predictive biomarker associated with improved overall survival (OS)." (PMID 38291266, 2024). "Epigenetic silencing of the DNA repair enzyme O6-methylguanine-DNA methyltransferase (MGMT) has emerged as a prognostic and predictive marker in patients with glioblastomas (GBM)." (PMID 38404571, 2024). "CheckMate 143 confirmed the safety and tolerability of nivolumab in patients with newly diagnosed glioblastoma, median overall survival with nivolumab was 33.38 (16.2 to not estimable) and 16.49 (12.94-22.08) months in patients with methylated and unmethylated MGMT promoter, respectively." (PMID 39555054, 2024). "Results: a total of 56 patients with IDH-mutant gliomas and 60 patients with IDH-wildtype glioblastomas (GBM) (37 with methylated MGMT and 17 with unmethylated MGMT) were diagnosed by 2021 WHO classification criteria." (PMID 39594235, 2024). "Furthermore, the cell lines with MGMT promoter region methylation exhibited increased sensitivity to temozolomide, consistent with the impact of methylation on treatment outcomes in patients with glioblastoma." (PMID 38357209, 2024). "In conclusion, our study showed that along with well-known prognostic factors such as KPS, MGMT status, and surgical extent, pre-RT serum biomarkers, including the De Ritis ratio and glucose level, also had prognostic value in elderly patients with glioblastoma treated with TMZ-based chemoradiation." (PMID 38288092, 2024). "However, the same study suggested that IDH-wildtype glioblastomas with unmethylated MGMT-promoter may benefit from combined chemotherapeutic modalities to improve prognosis." (PMID 38827324, 2024). "Importantly, the impact of DIAPH3 was more prominent in MGMT-methylated glioblastomas." (PMID 38454929, 2024). "However, with non-perfect sensitivity and specificity, these values could be a part of future prediction algorithms in order to estimate the MGMT status of glioblastomas in vivo." (PMID 36900177, 2023).
glioblastoma (continued). "We speculate that glioma subtypes that have longer periods of disease latency after treatment, such as low-grade gliomas or MGMT-methylated glioblastoma, may have a higher burden of senescent cells than gliomas that recur more rapidly, such as MGMT-unmethylated glioblastoma." (PMID 38030881, 2023). "Therefore, reinvestigation of the methylation status of MGMT might be indicated in glioblastoma patients with prolonged survival to be able to estimate the therapeutic effect of temozolomide at recurrence." (PMID 37641156, 2023). "In addition, TMZ resistance in glioblastoma multiforme is mediated by MGMT." (PMID 37086071, 2023). "Moreover, precursors of miR-181d-5p and miR-409-3p may be useful to reduce the levels of MGMT (O-6-methylguanine DNA methyltransferase) involved in temozolomide response in glioblastoma." (PMID 37631335, 2023). "In addition, the phosphorylation of STAT3 increases in MGMT-overexpressed glioblastoma cells." (PMID 38264122, 2023). "In addition, the combination of nedisertib and radiotherapy is being evaluated in phase I trials with MGMT unmethylated glioblastoma or gliosarcoma (NCT04555577), advanced head and neck cancer (NCT04533750) and phase I/II trials in patients with pancreatic cancer (NCT04172532)." (PMID 37637936, 2023). "Thus, elevated fatty acid levels in obese patients might compromise the therapeutic response to alkylating chemotherapy in MGMT methylated glioblastoma." (PMID 35704157, 2022). "Here, we constructed a decision tree according to the age, sex, IDH.Mutation, MGMT.promoter.methylation and SRS.score of glioblastoma patients in TCGA-GBM cohort." (PMID 36561336, 2022). "Moreover, at least in O6-methylguanine-DNA methyltransferase (MGMT)-deficient tumors, repeated TMZ treatments very likely lead to an accumulation of critical DNA damages that trigger cell death, which is supported by our studies on glioblastoma cells in vitro." (PMID 35785203, 2022). "Likewise, MGMT status impacts the management of patients with recurrent glioblastomas." (PMID 35804921, 2022). "Indeed, [18F]FDOPA PET-guided dose-escalated radiation therapy significantly improved the overall survival in the subgroup of O6-methylguanine-DNA methyltransferase (MGMT) methylated glioblastoma patients and the progression-free survival in MGMT unmethylated glioblastoma patients." (PMID 35205625, 2022). "Moreover, a recent study suggested that dual alkylator therapy with temozolomide and lomustine might improve survival compared with standard temozolomide therapy in patients with newly diagnosed glioblastoma with an MGMT-methylated promoter." (PMID 35447948, 2022). "As the expression of MGMT by glioblastoma cells has been linked to resistance to the alkylating agent temozolomide, this TNT-mediated transfer of MGMT was proposed as spreading this MGMT-based resistance to TMZ among GBM cells." (PMID 35267518, 2022). "Glioblastoma (GBM) was diagnosed in 13 (including two recurrences), with nine MGMT methylated and two isocitrate dehydrogenase-1 (IDH-1) mutant." (PMID 36143263, 2022). "Thus, in the near future, nanopore sequencing might indeed be a lower cost and less time-consuming alternative method for MGMT gene methylation assessment and for methylome-based classification of glioblastomas." (PMID 35806153, 2022). "Moreover, as hypothesized for other biomarkers, the methylation status of the MGMT promoter as a possible prognostic factor has also been evaluated in patients with recurrent glioblastoma." (PMID 35626029, 2022). "Therefore, the histology is consistent with a grade 4 IDH-1 wild-type glioblastoma typically found in the elderly population, but her prognosis may be better than average due to the methylated promoter of MGMT." (PMID 36703629, 2022).
glioblastoma (continued). "Positive results could lead us to a more personalized decision making in glioblastoma treatment, in particular during the chemotherapy stage, allowing prolonged survival times in patients with methylated MGMT and moderate vascular tumors and avoiding toxicity in patients with high vascular tumors." (PMID 34771583, 2021). "Moreover, all glioblastoma patients with methylated and unmethylated MGMT promoters could benefit from TMZ treatment." (PMID 34256854, 2021). "Whether this glycolytic switch represents an attempt of the cells to resist to TMZ by impairing prodrug activation deserves in vivo evaluation, for example by testing the combined effect of MGMT inhibition and proton transporter inhibitors on the response of orthotopic glioblastomas to TMZ." (PMID 34769368, 2021). "A recent study with a multicenter cohort of 96 glioblastoma patients concluded that MGMT methylation may benefit overall survival only in patients with moderately vascularized glioblastomas, defined by MRI perfusion-based marker, such as relative cerebral blood volume (rCBV)." (PMID 34771583, 2021). "Moreover, in a phase III trial, cilengitide was assessed in combination with chemoradiotherapy (temozolomide) in patients bearing newly diagnosed glioblastoma with methylated O-6-methylguanine-DNA methyltransferase (MGMT) promoter (a prognostic biomarker for glioblastoma)." (PMID 34715893, 2021). "However, overexpression of miR-486-3p did not affect cell survival of A172 cells, indicating that miR-486-3p sensitized glioblastoma cells to TMZ might through MGMT." (PMID 32086739, 2020). "Our findings suggest that not only is MGMT implicated in resistance to TMZ but MPG, the first enzyme in base excision repair processing, is also involved, supporting its potential role as a target in anti-resistance chemotherapy for astrocytoma and glioblastoma." (PMID 33335215, 2020). "Epigenetic inactivation of O6‐methylguanine‐methyltransferase (MGMT) gene by methylation of its promoter is predictive of Temozolomid (TMZ) response in glioblastoma (GBM)." (PMID 32666673, 2020). "In addition, after TMZ treatment, glioblastoma cells expressing miR-486-3p had a significant decrease in the expression of MGMT and increase in the levels of phosphorylated histone H2AX (γ-H2AX, Markers of DNA double strand breakage) and cleaved caspase-3 compared with vector control cells." (PMID 32086739, 2020). "Our study seems to support the hypothesis that MGMT promotor status may not only add prognostic information in histologically defined glioblastoma, but also in astrocytic tumors without IDH mutation." (PMID 33184319, 2020). "In contrast, the clinical prognostic value of MGMT promoter methylation in grade IV gliomas remained unclear, although its significance as a predictor of treatment outcome to combined chemoirradiation with temozolamide in glioblastomas has been demonstrated in some studies." (PMID 32005184, 2020). "O6-methylguanine-DNA methyltransferase (MGMT) promoter methylation status has been considered a prognostic factor in newly diagnosed glioblastoma (GBM)." (PMID 33116181, 2020). "anaplastic astrocytoma cases had more MGMT promoter methylation (50%) than glioblastoma multiforme (GBM) (20%), more IDH1 R132H mutation (42%) than GBM (4.3%)." (PMID 33282092, 2020). "Therefore, incomplete or absence of molecular data on IDH mutation and MGMT methylation or mixing molecular subtypes when evaluating the impact of glioblastoma resection on survival is undesirable." (PMID 32766140, 2020). "In addition, prolonged cell culture leads to progressive hypermethylation of the MGMT promoter, approximately 80% of glioblastoma cell lines are MGMT hypermethylated, as compared to a 40% frequency of promoter hypermethylation in the initial clinical diagnosis." (PMID 33390879, 2020).
glioblastoma (continued). "Furthermore, adding GBM patients’ MGMT promoter methylation, age, and exosomal miR-181b expression information improves predictive significance and should be considered in all future research regarding predictive exosomal biomarkers for glioblastoma patients." (PMID 33050332, 2020). "Glioblastoma is the most common and aggressive type of cancer in the brain; its poor prognosis is often marked by reoccurrence due to resistance to the chemotherapeutic agent temozolomide, which is triggered by an increase in the expression of DNA repair enzymes such as MGMT." (PMID 33201894, 2020). "In total, 769 patients with newly diagnosed, contrast enhancing glioblastoma were screened, of whom we excluded 333 patients: 22 were excluded due to IDH mutation and 311 were excluded due to insufficient or missing molecular data on IDH mutation or MGMT methylation status." (PMID 32477929, 2020). "Thus, in light of the WHO 2016 reclassification, which now includes such molecular data, the association between CE and NCE glioblastoma resection and survival needs to be re-evaluated in a molecularly homogenous glioblastoma IDH-wildtype population, while considering MGMT promoter methylation." (PMID 32766140, 2020). "Furthermore, EGCG selectively decreased MGMT levels in glioblastoma multiforme cells by preventing translocation of β-catenin to the nucleus, thereby avoiding the removal of temozolomide-produced O6-methylguanine and helping to resensitize cells resistant to this drug." (PMID 33330091, 2020). "Besides, O-6-methylguanine-DNA methyltransferase (MGMT) promoter methylation has been found to increase the chemosensitivity of temozolomide treatment, and it is a strong prognostic biomarker in patients with glioblastoma." (PMID 33240891, 2020). "Despite these well-known relationships, the prognosis of glioblastoma, which account for up to 70% of high-grade malignant glioma, is bleak as the median length of survival is only 14.6 months (12.6 and 23.4 months in the MGMT-unmethylated and MGMT-methylated subgroups, respectively)." (PMID 30925722, 2019). "Recurrence in patients with glioblastoma (GBM) is inevitable resulting in short survival times, even in patients with O-6-Methylguanine-DNA Methyltransferase (MGMT) methylation." (PMID 30814573, 2019). "Moreover, upon JUN, CEBPB and HDAC3 knockdown, the expression levels of MGMT decreased significantly, suggesting that these genes could regulate drug resistance of glioblastoma by mediating MGMT status." (PMID 30775317, 2019). "In fact, in the case of glioblastoma (GBM) patients, standard of care generally involves analysis of MGMT promoter methylation status in resected tumor tissue as the key predictive factor of TMZ efficacy." (PMID 30274152, 2018). "Therefore, FM1911 could be a candidate for future testing to counteract TMZ resistance in MGMT‐positive glioblastomas." (PMID 29761922, 2018). "FM19G11 could potentially be used to counteract TMZ resistance in MGMT‐positive glioblastomas." (PMID 29761922, 2018). "Results from one study showed that, as in adults, in the majority of paediatric glioblastoma cell lines TMZ resistance was linked to a lack of promoter methylation of the gene encoding the repair protein DNA methyltransferase MGMT (O6-methylguanine-DNA-methyl-transferase)." (PMID 28704425, 2017). "In this paper, the authors investigate texture features as potential imaging biomarkers for capturing the MGMT methylation status of glioblastoma multiforme (GBM) tumors when combined with supervised classification schemes." (PMID 27277032, 2016). "Furthermore, miR-181d expression inversely correlated with that of MGMT mRNA in glioma tissue specimens; moreover, overexpression of miR-181d in A1207, LN340 and T98G glioblastoma cell lines reduced MGMT mRNA levels and conferred pro-apoptotic sensitivity to temozolomide." (PMID 26035292, 2015).